INS (insulin)
Diseases named in the same sentence as INS in open-access papers (continued):
Sharing a sentence is not in itself a finding about the gene and the disease.
Insulin resistance (continued). "A possible explanation is an impaired insulin signaling through PI3K signaling pathway and the increased vascular inflammation noted in insulin resistance which can decrease nitric oxide (NO) production and increase Endothelin-1 (ET-1) secretion leading to raised blood pressure." (PMID 27597980, 2016). "In addition, the homeostasis model assessment-insulin resistance (HOMA-IR) increased, indicating the establishment of insulin induced by 8-week HFD feeding." (PMID 27793043, 2016). "Despite increased β-cell function and anti-inflammatory effects, no improvement in insulin sensitivity was observed and, thus, it is not a complete therapy for obesity induced insulin resistance." (PMID 27128935, 2016). "Px rats are a good model to examine the relationship between β-cell function and insulin resistance and β-cell expansion since they are a non-obese and insulin-insufficient type 2 diabetic model with characteristics relevant to Asian type 2 diabetes." (PMID 26978400, 2016). "Plasma insulin levels of HFD-fed F13a1−/− mice were significantly lower compared to F13a1+/+ mice – demonstrating that F13a1−/− mice are resistant to developing hyperinsulinemia, which often accompanies insulin resistance." (PMID 27759118, 2016). "While this exhibited insulin resistance in vivo and impaired proximal insulin signaling in vitro, no impairment of preadipocyte differentiation ex vivo was reported." (PMID 27766312, 2016). "Several models have incorporated fasting plasma insulin to indirectly measure insulin resistance, including a homeostasis model assessment of insulin resistance (HOMA-IR), a quantitative insulin sensitivity check index (QUICKI) and the fasting glucose/insulin ratio (FGIR)." (PMID 27824069, 2016). "First, serum insulin levels were not analyzed and homeostasis model of assessment-insulin resistance was not calculated." (PMID 27121855, 2016). "In contrast to the severe insulin resistance seen in SHORT syndrome, haploinsufficiency or complete knockout of p85α alone, p85α, p55α, and p50α together, p55α and p50α together, or p85β all increase insulin sensitivity in mice." (PMID 27766312, 2016). "Considering the effect of thiazolidinedione in CTRP13, upregulation of CTRP13, and correlation between CTRP13 and insulin resistance, it seems likely that CTRP13 can be considered as a part of complicated signaling pathway involving insulin sensitizer effect of thiazolidinedione." (PMID 28033351, 2016). "Since PTEN inhibition restores vascular insulin sensitivity, decreased by TNF-α and HFD, PTEN may be considered a major contributor to TNF-α-induced insulin resistance." (PMID 27562094, 2016). "Interestingly isorhamnetin attenuated the serum insulin and leptin levels in DIO mice, indicating an improvement of insulin resistance and leptin resistance." (PMID 26775807, 2016). "Third, the core of MetS is insulin resistance, which we were unable to measure due to the lack of plasma insulin levels in our present study." (PMID 26758511, 2016). "Although IRS-1 serine phosphorylation by SFA is considered as an emerging detrimental factor in insulin sensitivity, a growing lines of evidence have suggested that the reduction of INSR expression also promotes the pathogenesis of insulin resistance and diabetes." (PMID 28036389, 2016). "In patients not currently treated with insulin, and particularly for those with insulin resistance, it is recommended that metformin be initiated or continued if FPG > 126 g/dL or HbA1c is >6.5 %." (PMID 27405306, 2016). "Despite the generally accepted fact that obese PCOS subjects have insulin resistance and insulin sensitivity in these patients is less than obese non-PCOS women, the findings in non-obese PCOS patients are controversial." (PMID 27351028, 2016).
Insulin resistance (continued). "Independent of calorie intake, 32% PRO tended to result in lower homeostatic model assessment of insulin resistance (HOMA-IR) values compared to 10% PRO, while insulin and homeostatic model assessment of β-cell function (HOMA-β) values were lower in CR than AL, regardless of protein intake." (PMID 27649241, 2016). "Using fasting glucose and insulin measurements at both baseline and the second year of follow-up, the homeostatic model assessment of beta-cell function (HOMA-β) and homeostatic model assessment of insulin resistance (HOMA-IR) were calculated." (PMID 27266903, 2016). "Of note, insulin resistance, but not impaired insulin secretion or hepatic insulin uptake, was shown to be the predominant feature of HCV-associated glucose intolerance in non-diabetic RTRs." (PMID 26735686, 2016). "The current study showed that chronic olanzapine treatment induces a significant increase of fasting glucose and insulin levels and insulin resistance in female Balb/c mice without weight gain." (PMID 27973621, 2016). "The correlation between DDR1 and IR and the finding that insulin may also upregulate DDR1, raise the possibility that insulin resistance and compensatory hyperinsulinemia may enhance DDR1 in neoplastic tissues." (PMID 26655502, 2016). "We did not measure insulin sensitivity in the present study, but several previous studies have shown that deficiency of liver-derived IGF-I in mice is characterized by insulin resistance." (PMID 26627099, 2016). "Insulin tolerance test (ITT) of F13a1−/− and F13a1+/+ mice on chow diet showed that mice have similar insulin sensitivity, however, while F13a1+/+ mice develop insulin resistance on HFD, F13a1−/− mice were protected and showed normal insulin sensitivity (as on chow diet)." (PMID 27759118, 2016). "In addition, HF diet fed rats had almost two fold less insulin sensitivity, as determined by homeostasis model assessment (HOMA) of insulin resistance." (PMID 27134637, 2016). "The lack of insulin levels and insulin resistance index by homeostasis model assessment (HOMA-IR) determinations is a limitation of this study." (PMID 26823979, 2016). "Insulin resistance is a state in which cells do not respond properly to insulin (even if it is available in the blood), which leads to hyperinsulinemia (high blood insulin)." (PMID 25972911, 2015). "Insulin resistance is a chronic condition in which the hormone insulin fails to activate its own signaling cascade, resulting in hyperglycemia." (PMID 25960614, 2015). "The treatment with LA did not affect significantly plasma glucose and insulin levels and insulin resistance in ZDF rats." (PMID 26413386, 2015). "Assessment of the insulin resistance index based on the fasting blood glucose and insulin serum levels (HOMA-IR) did not reveal differences among the groups at each time point." (PMID 26248027, 2015). "T2DM (formerly noninsulin-dependent DM) is a metabolic disorder due to hyperglycemia in the context of insulin resistance and relative lack of insulin." (PMID 26448950, 2015). "Hyperinsulinemia represents a surrogate measure for insulin resistance in nondiabetics, as well as in T2D patients with significant residual insulin secretion capacity." (PMID 26089903, 2015). "Deterioration was accompanied by a non-significant decrease in insulin secretion and a non-significant increase in insulin resistance." (PMID 26248027, 2015). "This study was designed to determine whether changes in PCNT expression occur in high-fat-induced insulin resistant (IR) mice in vivo and to explore the in vitro mechanism whereby PCNT regulates insulin secretion, using a mouse pancreatic cell line (MIN6)." (PMID 26083368, 2015). "Low insulin sensitivity is referred to as insulin resistance, in which insulin fails to efficiently modulate glucose uptake, production, and storage in insulin-sensitive tissues." (PMID 25888638, 2015).
Insulin resistance (continued). "Agonist-induced activation of PPARγ has been demonstrated to increase insulin sensitivity and thiazolidinediones (TZD) are used clinically to reduce insulin resistance and hyperglycemia in patients with type 2 diabetes, although these drugs are also associated with weight gain." (PMID 26317347, 2015). "The metabolic disorder whereby cells in the body do not respond to insulin properly is known as insulin resistance." (PMID 26488726, 2015). "Unfortunately, we did not have data on plasma insulin levels for this cohort so we were unable to evaluate the relationship between UA and insulin resistance." (PMID 26618358, 2015). "The Insulin Resistance Index of the HFHSD group was significantly higher than that of the control group during the last seven months of the study, which indicates that the HFHSD group had lower insulin sensitivity than the control group." (PMID 26358367, 2015). "Conversely, high dose of insulin experienced increased peripheral insulin resistance in APOE negative patients." (PMID 26136647, 2015). "Other methods, such as the minimal model approximation of the metabolism of glucose (MMAMG) and homeostasis model assessment to estimate insulin resistance (HOMA-IR), can be also used; however, they are indirect derivatives computed from fasting insulin and glucose determinations." (PMID 25961050, 2015). "Positive correlations of these modules enriched for mitochondrial function with insulin sensitivity, and negative correlations with BMI in both AA and CA subjects, indicate that a common molecular mechanism may be involved in obesity-associated insulin resistance." (PMID 25868721, 2015). "Insulin stimulation of AKT phosphorylation (Ser473) was markedly reduced (by ∼50%) in livers of 3w SRD CBA as compared with 3w CD CBA mice, providing molecular evidence that the SRD provoked hepatic insulin resistance in these mice." (PMID 26085100, 2015). "In mice, we found that prolonged insulin treatment resulted in reduced glucose and insulin tolerance, suggesting that insulin alone, independent of other variables, is capable of inducing insulin resistance." (PMID 26682540, 2015). "The constant elevated level of basal insulin, irrespective of its origin, usually leads to generalized insulin resistance." (PMID 26521236, 2015). "Glucose tolerance is not regulated by the degree of insulin resistance alone, but by the capability of the β-cell to provide and keep an amount of circulating insulin able to compensate for it." (PMID 25938808, 2015). "T2DM is a multi-factorial disease characterized by peripheral insulin resistance, occasionally combined with an absolute lack of insulin." (PMID 25333294, 2015). "Type 2 DM, characterized by insulin resistance and a relative lack of insulin secretion, accounts for as much as 90% of all cases of DM and its prevalence is increasing." (PMID 26508984, 2015). "In contrast, we identified decreased expression of selected genes involved in insulin resistance in adipose tissue, including TLR3, FOS, and PRL, which could induce insulin sensitivity." (PMID 26089598, 2015). "The reduced insulin and elevated NEFA concentrations during the early postpartum, determined that the in the present study RQUICKI decreased during this period, which is indicative of increased reduced insulin resistance." (PMID 26475473, 2015). "In the current study, evaluation of peripheral insulin resistance was based on fasting glucose and insulin levels and vitamin D was not correlated with insulin resistance." (PMID 28913035, 2015). "Insulin resistance is present even in simple obesity, without hyperglycemia, indicating a fundamental abnormality of insulin signaling in states of excess adipose tissue mass." (PMID 25688211, 2015). "Fasting serum lipid, insulin, and non-esterified fatty acid were assessed and transformed to insulin resistance index, HOMA-IR and Adipo-IR." (PMID 26458397, 2015).
Insulin resistance (continued). "In this study, we observed that PTP1B has three O-GlcNAc sites: Ser104, Ser201, Ser386; O-GlcNAcylation of PTP1B is increased in insulin resistance; and intervention PTP1B O-GlcNAcylation can recover insulin sensitivity and improve lipid deposition in HepG2 cells." (PMID 26402673, 2015). "In our investigation, the insulin treatment of GK rats did not affect hepatic PKCε activation, suggesting that the insulin treatment modulated PKCε activation in a way to avoid hepatic insulin resistance." (PMID 26398746, 2015). "Arising either from beta cell dysfunction and insulin resistance, or from autoimmune cell-mediated pancreatic islet cell destruction and resultant lack of insulin, treatments are usually aimed at glycaemic control, or reducing insulin resistance." (PMID 26239553, 2015). "Owing to the large size of the ELSA-Brasil study, we were not able to assess insulin resistance and secretion using more sophisticated methods, and thus relied on the relatively more crude plasma insulin levels and HOMA measurements." (PMID 25978631, 2015). "Insulin resistance is likely to be involved in the increased chylomicron production, since the normal acute suppression of postprandial chylomicron secretion, by insulin, is absent in patients with type 2 diabetes." (PMID 25725623, 2015). "Before supplementation, the concentration of fasting Glu and insulin and insulin resistance evaluated from HOMAIR were not significantly different between Cr/Gly/Glu and Cr/Gly/Glu/Ala groups." (PMID 26167296, 2015). "Exposure of sham mice to arsenic significantly increased blood glucose, decreased plasma insulin, and impaired glucose tolerance, but did not induce insulin resistance." (PMID 25859628, 2015). "The plasma concentrations of specific BCAA, such as valine, show significant positive correlation with the homeostatic model assessment (HOMA) of insulin resistance, and an overall increase in the BCAA has been described as contributor to the insulin-resistant state that accompanies human obesity." (PMID 25781654, 2015). "FTO polymorphisms are associated with type 2 diabetes which is a metabolic disorder in the context of insulin resistance and relative lack of insulin due to dysfunction of pancreas islet cells." (PMID 26018652, 2015). "Compared to control subjects, women with GDM exhibited elevated values for plasma glucose, insulin, and insulin resistance (IR), and showed reduced HOMA pancreatic β-cell function (HOMA-B), insulin sensitivity index (ISI), insulinogenic index, and corrected insulin response at 24–28 weeks gestation." (PMID 25915047, 2015). "As insulin resistance is one of the hallmarks of palmitate-induced lipotoxicity, we tested a wide range of palmitate dosages for its effects on insulin-induced AKT phosphorylation (AKT-P at Ser473) (data not shown)." (PMID 26075729, 2015). "The risks of type 2 diabetes, early IGT, and insulin resistance were perfectly predicted by comparing fasting glucose levels to the estimated Matsuda Index 3 (fasting levels of 10- and 12-(Z,E)-HODE/linoleic acids, insulin, and leptin/adiponectin)." (PMID 26132231, 2015). "Given the important role of Mg in insulin action, it is also possible that the higher prevalence of hypomagnesemia in women contributed to poorer glucose control and insulin resistance rather than just being a consequence of the abnormalities." (PMID 25947295, 2015). "Given that enhanced activation of JNK and NF-κB pathways may induce insulin resistance via phosphorylation of insulin receptor substrate-1 (IRS-1) on serine 307 and dephosphorylation of Akt31, we examined the effects of WEGL on insulin activity." (PMID 26102296, 2015). "These increased miRNA levels were independent of insulin, insulin resistance and of hyperandrogenaemia in women with PCOS." (PMID 26582398, 2015).
Insulin resistance (continued). "A positive and statistically significant correlation between serum ferritin and oxidative stress markers (carbonyl groups, glycated HB, and AOPP), hepatic damage markers (GGT and SGOT), and insulin resistance related parameters (HOMA, blood insulin, and fasting glucose) was observed." (PMID 26451235, 2015). "Insulin resistance, the lack of responsiveness to insulin, is at the basis of the pathogenesis of many metabolic disorders, widespread in the world population and constantly growing." (PMID 26383020, 2015). "Inhibitors of PTP 1B can potentially ameliorate insulin resistance and normalize plasma glucose and insulin levels without inducing hypoglycemia." (PMID 26213526, 2015). "Plasma insulin concentrations and HOMA-IR values were significantly higher in the T2DM group in comparison to the NGT group (p<0.001, t-test); indicating the heightened insulin resistance of the T2DM group." (PMID 25742416, 2015). "In the present study, the significant change in insulin concentration and insulin resistance was independent of fasting glucose concentration." (PMID 26593941, 2015). "Compared with the control group, the level of fasting insulin and the homeostasis model assessment of insulin resistance (HOMA2-IR) were higher in the DM group, while the homeostasis model assessment of β-cell insulin secretion (HOMA2-%β) and the first-phase peak ratio were lower (P<0.05)." (PMID 25574243, 2015). "Documented data revealed that prostate size correlates positively with the fasting glucose level (r =0.186, p = 0.007), but not with BMI, testosterone, insulin level, or insulin resistance (each p > 0.05)." (PMID 26576637, 2015). "In summary, these findings showed that the more MEHP was metabolised to 6-OH-MEHP, the greater the state of insulin resistance in a given subject, whereas the lesser MEHP was metabolised, the lesser insulin was required, the better the FGIR, the lower the HOMA index, and the higher the WBISI." (PMID 25706863, 2015). "Due to higher glucose levels and similar or lower insulin levels, homeostatic model assessment of insulin resistance (HOMA-IR) is higher in KO vs. WT on chow and HFD, but not significantly." (PMID 26047815, 2015). "To further characterize the protection against diet-induced insulin resistance observed in aP2-HMGA1 mice, we analyzed the insulin-stimulated phosphorylation of Akt (p-Akt) as well as 2-deoxyglucose (2-DG) uptake in WAT, liver and skeletal muscle in these mice." (PMID 26411793, 2015). "In Korea, previous studies reported that 65 % of diabetic subjects are non-obese and that impaired insulin secretion is more prominent than insulin resistance in the pathogenesis of type 2 DM, even in the status of impaired glucose tolerance." (PMID 26471283, 2015). "In rodent models of insulin resistance, the TR agonist KB141 was shown to elicit striking improvements in glycemic control and insulin sensitivity when administered to ob/ob mice, while the agonist MB07811 has been reported to reduce fasting glucose levels in diet-induced obese mice." (PMID 25849936, 2015). "The fasting insulin levels, first-phase peak ratio, HOMA2-IR and HOMA2-%β in the patients were all markedly improved compared with the values prior to therapy, which indicated that insulin resistance and β-cell function had been improved." (PMID 25574243, 2015). "In a recent series of papers, LeRoith and colleagues utilized a mouse model of genetically induced insulin resistance that develops hyperinsulinemia without obesity to examine how insulin signaling impacts mammary tumor growth in vivo." (PMID 26029167, 2015). "Additionally, leptin, insulin, and homeostasis model assessment (HOMA) index were analyzed in obese and normal-weight girls in order to determine the degree of insulin resistance." (PMID 25892992, 2015).